EGFR (epidermal growth factor receptor)
Diseases named in the same sentence as EGFR in open-access papers (continued):
Sharing a sentence is not in itself a finding about the gene and the disease.
ovarian carcinoma (continued). "EGFR may not be a prognostic biomarker for patients with ovarian cancer." (PMID 38203692, 2023). "Given that approximately 70% of ovarian cancer cells express high levels of epidermal growth factor receptor (EGFR) and the involvement of this receptor in angiogenesis and metastasis processes, the inhibition of this receptor could offer a potential treatment for ovarian cancer." (PMID 35550636, 2022). "Importantly, our data demonstrated an expression of human epidermal growth factor receptor (HER)‐2 on high‐grade ovarian tumors, which can serve as an efficient tumor antigen to target CD3 TIL or selectively Vγ9‐expressing γδ T cells by bispecific antibodies (bsAbs) to ovarian cancer cells." (PMID 31833593, 2020). "Furthermore, treatment of ovarian cancer cells with erlotinib, a selective inhibitor of the EGFR kinase domain, completely blocked the proliferative response of the cells to SPINK1, demonstrating that EGFR signaling is required for SPINK1-stimulated proliferation." (PMID 30778387, 2019). "Corresponding to this data, we showed in a preclinical study with different ovarian cancer cell lines that dual anti-EGFR blockade led to neither synergistic antiproliferative effect in anti-EGFR-sensitive cells nor de novo anti-EGFR sensitivity in anti-EGFR-resistant cell lines." (PMID 31546690, 2019). "While data evaluating the predictive potential of EGFR and related markers in ovarian cancer have thus far not been encouraging, it remains possible that EGFR expression or gene copy number in combination with other markers may yet become useful for stratification of response to treatment." (PMID 28740577, 2017). "Ovarian cancer cells that are not growth suppressed by trastuzumab treatment are still responsive to the therapeutic agent and trastuzumab could be utilized as a primer for EGFR-targeted therapy." (PMID 26751490, 2016). "However, both ovarian carcinoma cell lines express similar EGFR basal level (data not shown)." (PMID 25627260, 2015). "We show that its synergistic anti-cancer effect, when combined with paclitaxel, is independent of EGFR, ERBB2, or ERBB4 antagonism in human ovarian cancer cell models." (PMID 34347777, 2021). "Despite the contribution of EGFR-mediated EMT to therapy resistance, a recent Cochrane meta-analysis demonstrated little or no survival benefit from anti-EGFR treatment in ovarian cancer patients." (PMID 31213009, 2019). "These authors showed that HE4 inhibited the proliferation of ovarian cancer cells via MAPK and PI3K/AKT signaling pathways in vitro, but did not affect EGFR phosphorylation." (PMID 31210752, 2019). "Despite these advances, many patients simply do not respond or eventually develop resistance to therapy with the EGFR inhibitors, and none of the HER inhibitors have yet been approved for the treatment of ovarian cancer patients." (PMID 29731973, 2018). "Unlike EGFR and HER-2, very few studies have been conducted on HER-3 and HER-4 expression in ovarian cancers and in particular the co-expression all four members of the HER family and their prognostic significance." (PMID 29731973, 2018). "Monensin was shown to target multiple cancer-related signaling pathways including Elk1/SRF, AP1, NFκB and STAT, and suppress the expression of EGFR, but not IGF-1R, in ovarian cancer cells." (PMID 26639992, 2015). "Here we show that pretreatment of human ovarian carcinoma tumors with sub-optimal doses of the VEGFR targeting tyrosine kinase inhibitor axitinib, but not the EGFR targeting kinase inhibitor erlotinib, induces a transient period of increased tumor oxygenation." (PMID 25758612, 2015). "Therefore, we hypothesized that there would be crosstalk between the PAFR and EGFR pathways, which may be one of reasons for the resistance of cancer cells to drugs, and that the combined targeting of PAFR and EGFR would synergistically inhibit ovarian cancer progression." (PMID 24886678, 2014).
ovarian carcinoma (continued). "In this study, we demonstrated that the apoptotic effect of miR-491-5p in ovarian cancer cells is related to both BCL-XL inhibition and BIM stabilization through inhibition of EGFR signalling, as long as downstream effectors are not constitutively activated." (PMID 25299770, 2014). "Several EGFR targeted therapies such as monoclonal antibodies, small molecule inhibitors or RTK inhibitors failed to pass phase II clinical trials of ovarian cancer, giving rationale to develop newer therapies." (PMID 22952709, 2012). "Although the role of EMT in regulating metastasis in ovarian cancer cells is still not clear, overexpression of EGFR and constitutively active STAT3 have been shown in clinical specimens and ovarian cancer cell lines." (PMID 19088723, 2009). "EGFR and HER-2 are important targets but none of the monoclonal antibodies or small molecule tyrosine kinase inhibitors specific for the HER members has been approved for the treatment of patients with ovarian cancers." (PMID 29731973, 2018). "In spite of no change in EGFR activation after cancer spreading of SKA and SKCXCR2 cells, the NF-κB signaling pathway appears to conserve CXCR2-driven ovarian cancer progression throughout the whole process including initiation, promotion and progression phases." (PMID 27723802, 2016). "Furthermore, as described in detail previously, CXCR2 positive ovarian cancer cells enhanced more the promoter activity and mRNA levels of CXCL1 and 2 by NF-κB potentiation through EGFR-activated Akt compared to CXCR2 negative cells." (PMID 27723802, 2016). "While EGFR and RAS mutants are not commonly observed in ovarian cancer, activation of these well-studied oncogenes may still play an important role in progression and survival in ovarian cancer." (PMID 23323831, 2013). "Both ovarian carcinoma cell lines, SKOV-3 and SKOV3.ip1, showed biphasic binding of the pre-targeted liposomes indicating that pre-targeting results in liposome binding both in EGFR-specific and non-specific manner." (PMID 22844475, 2012). "The status of the EGFR and HER2-neu genes has not been fully defined in ovarian cancer." (PMID 18182111, 2008).
gastric cancer (742 papers, 1990 to 2026). A primary or metastatic malignant neoplasm involving the stomach. "ERBB2, also identified as an upregulated gene in gastric cancer, encodes a 185 kDa transmembrane glycoprotein belonging to the epidermal growth factor receptor (EGFR) family." (PMID 40141751, 2025). "Clinical survival analysis identified four core proteins (CASP3, TNF, AKT1, and EGFR) whose abundance was associated with survival status in gastric cancer patients." (PMID 40573220, 2025). "Distant metastasis is the major cause of gastric cancer mortality, and epidermal growth factor receptor (EGFR) activation plays critical roles in gastric cancer dissemination." (PMID 39838173, 2025). "EGFR is overexpressed in about 50% of esophageal cancers and 30% of gastric cancers and is associated with poor prognosis and resistance to chemotherapy." (PMID 39417449, 2024). "In human cancers, EGFR has been associated with a poor prognosis in gastric carcinoma and head and neck SCC." (PMID 38248333, 2024). "EBV positive gastric cancer is associated with increased Ki-67 and decreased EGFR expression and a shorter resection margin due to the prominent lymphoid stroma." (PMID 37285389, 2023). "In previous studies, imaging radiomics and line drawings have been used to predict lymph node metastasis and prognosis in lung, colorectal, bladder, kidney, and gastric cancers, invasiveness of lung nodes, and epidermal growth factor receptor mutations." (PMID 37007065, 2023). "Gastric cancers are caused primarily due to the activation and amplification of the EGFR or HER2 kinases resulting in cell proliferation, adhesion, angiogenesis, and metastasis." (PMID 38186572, 2023). "Numerous studies showed a relation between the EGFR gene polymorphism and advanced stages of various cancers, such as lung and gastric cancer." (PMID 35463723, 2022). "The epidermal growth factor receptor (EGFR) has obvious mutations in gastric cancer and EGFRVIII protein expression cannot be detected in normal gastric epithelial cells." (PMID 36568183, 2022). "Studies have found that gastric cancer cells showed periodic mutations in some key oncogenes such as Her2, epidermal growth factor receptor (EGFR), PI3K, mTOR, or c-Met15." (PMID 34326374, 2021). "BBR has been shown to suppress growth and cause apoptosis in gastric cancer cell lines owing to the inhibition of EGFR signaling, which includes STAT3 phosphorylation." (PMID 34885950, 2021). "In particular the abundance of EGFR has been reported to be associated with cetuximab response in gastric cancer." (PMID 32119655, 2020). "The overexpression of HER-2 and EGFR is associated with poor prognosis and has been reported in approximately 30%–50% of gastric cancers." (PMID 31318186, 2019). "Forth, the response rate of conventional targeted therapy is modest in target-positive patients, with 47% in HER-2 mutated gastric cancer, 71.2% for gefitinib in EGFR-mutated NSCLC, 71% for osimertinib for EGFR T790M mutated NSCLC, etc." (PMID 31766180, 2019). "The overexpression of EGFR is associated with a more advanced stage of the gastric cancer and its spread to lymph nodes, and consequently, with a poor prognosis." (PMID 31491956, 2019). "Approximately 30–40% of human gastric cancers show amplification of RTK genes, including EGFR, and EGFR expression is associated with poor prognosis of patients with gastric cancers." (PMID 30700829, 2019). "In summary, our study results showed differentially regulated lncRNAs and gastric cancer-associated genes such as EGFR, KLF4, DNMT1 and AGO4 are candidates of ceRNA network in gastric cancer." (PMID 29719612, 2018). "Overexpression of EGFR is detected in 27–44% of gastric cancer cases and is associated with a poor prognosis." (PMID 30237423, 2018).
gastric cancer (continued). "Human epidermal growth factor receptor-2 (HER-2), a transmembrane tyrosine kinase receptor belonging to the family of epidermal growth factor receptor (EGFR), is an important gastric cancer target encoded by the ErbB2 gene located on chromosome 17q21." (PMID 29986466, 2018). "Gastric cancers frequently overexpress the epidermal growth factor receptor (EGFR), which has been implicated in pathological processes including tumor cell motility, invasion and metastasis." (PMID 29237412, 2017). "Here the authors show that gastric cancer cells send EGFR through exosomes to the liver where it causes the establishment of a favourable microenvironment thus promoting metastasis." (PMID 28393839, 2017). "EGFR overexpression was observed in 27-44% of resected gastric cancer tissues and was often associated with poor prognosis." (PMID 26848976, 2016). "An approach to characterization of dual target engagement is also presented for an array of lung and gastric cancer cell lines that reflect diversity in the mutational status of EGFR and c-MET." (PMID 26260789, 2015). "We identified molecules whose expression is closely associated with high ND in gastric cancer and we confirmed a correlation between EGFR expression and high ND." (PMID 25154973, 2015). "Some earlier studies analyzing 82–511 gastric cancers linked EGFR amplification to advanced and undifferentiated cancers and poor prognosis." (PMID 25649416, 2015). "Overexpression of EGFR is associated with gastric cancer and there are several drugs such as Gefitinib, Erlotinib, and Ceutuximab that target EGFR mutations either in combination or as single agents." (PMID 25025766, 2014). "Helicobacter pylori transactivates the Epidermal Growth Factor Receptor (EGFR) and predisposes to gastric cancer development in humans and animal models." (PMID 25437333, 2013). "Somatic mutations and altered regulation of EGFR pathway genes have been widely implicated in the development and prognosis of esophageal and gastric cancers." (PMID 23874846, 2013). "EGFR overexpression has been reported in approximately 30% to 50% of gastric cancers and is associated with poor prognosis." (PMID 24330856, 2013). "Few studies have comprehensively examined the association between germline genetic variants in the EGFR pathway and risk of esophageal and gastric cancers." (PMID 23874846, 2013). "This suggests that PKG II not only inhibits the proliferation but also induces the apoptosis of gastric cancer cells, and the two effects are associated with the blockage of EGFR activation by this kinase." (PMID 24273605, 2013). "Expression of EGFR in resected gastric cancer has been linked to shorter overall survival, more advanced tumor stage, and lymph node metastases in some studies, but not in others." (PMID 23153332, 2012). "Overexpression of human epidermal growth factor receptor (EGFR) has been detected in gastric cancer (GC) and is associated with poor outcomes." (PMID 22139134, 2012). "Our data indicated that ERBB2 and EGFR genetic abnormalities were associated with the prognosis of gastric cancer." (PMID 21689422, 2011). "Previous studies performed in large number of patients also demonstrate that K-ras mutation or increased EGFR gene copy number is an uncommon genetic event in gastric cancer." (PMID 19127259, 2009). "The mutational analysis of the kinase domain of EGFR revealed the presence of mutations in 2.6% of 77 gastric carcinomas." (PMID 18199332, 2008). "From the 77 gastric carcinomas analysed, EGFR mutations in exons 18–21 were detected in 2.6% (2/77) of the cases." (PMID 18199332, 2008). "The activation of EGFR signaling is closely associated with cellular interaction between cancer cells and the surrounding cells, which can induce the migration and invasion of cancer cells, including lung, colon, and gastric cancer cells and HCC." (PMID 38673992, 2024).
gastric cancer (continued). "Moreover, the overexpression of c-CBL, CBL-b, and EGFR exhibited a significant association with the invasion and progression of gastric cancer." (PMID 39130630, 2024). "Similarly, EGFR is more abundant in the exosomes of gastric cancer patients, making it a potential diagnostic molecule." (PMID 37456253, 2023). "Moreover, high Ki-67 expression and low expression of EGFR expression have been demonstrated to be associated with EBV-positive gastric cancer." (PMID 37285389, 2023). "High EGFR expression is closely associated with gastric cancer." (PMID 37285389, 2023). "Additionally in gastric cancer, the participation of Rcan2 in tumor progression has been associated with EGFR, nuclear β-catenin, MMP7, laminin-γ2, and VEGF." (PMID 36267816, 2022). "Agents targeting HER2, pSTAT3, EGFR, and angiogenesis-associated molecules may be feasible for the treatment of BM from gastric cancer." (PMID 36338733, 2022). "In addition, our team previously reported that the level of the phosphorylated NDRG1 protein (NDRG1-pT346) is significantly associated with EGFR, EGFR-pY1068, and EGFR-pY1173 protein expression in gastric cancer." (PMID 34385595, 2021). "In summary, CD148 may serve as a prognostic factor in gastric cancer, and its downregulation might be a molecular abnormality linked to oncogenesis and metastasis of gastric cancer through EGFR phosphorylation and subsequent downstream signaling activation." (PMID 32201537, 2020). "Lastly, although CT texture features might correlate with immunochemical biomarkers such as E-cadherin, Ki67, VEGFR2, and EGFR in gastric cancer, the large feature numbers might cause false-discovery in our limited sample sizes." (PMID 31075839, 2019). "In addition, overexpression of EGFR mRNA was significantly associated with a worse prognosis in astrocytoma, breast, and gastric cancer patients." (PMID 30513863, 2018). "In addition to the lncRNAs, we also profiled the expression pattern of identified candidate gastric cancer-associated genes EGFR, FGFR2, KLF4, DNMT1 and AGO4 shortlisted from the analysis of genes by relative quantification." (PMID 29719612, 2018). "High EGFR expression might thus be the causative mechanism of the aggressiveness of gastric cancer with high ND." (PMID 25154973, 2015). "In this study, we determined that high EGFR expression may underlie the aggressive mechanism of advanced gastric cancer with high ND." (PMID 25154973, 2015). "Combined the data of relative EGFR expression, we found a significantly association between expression and methylation changes, which showed hypermethylation as an explanation of the stable maintenance of EGFR overexpression in gastric cancer." (PMID 25959250, 2015). "Consistent with that result, our data showed that NKX2.1 expression was closely associated with EGFR expression, and that expression of either molecule in primary gastric cancer may represent activation of the same pathway." (PMID 25154973, 2015). "Given the significance of this pathway, genetic variations in EGFR signaling proteins could correlate with predisposition to esophageal and gastric cancers." (PMID 23874846, 2013). "Whether such an approach with EGFR inhibitors would have a chemopreventative role in subjects who are at high risk of developing gastric cancer, who have failed H. pylori eradication therapy, requires consideration." (PMID 25437333, 2013). "Overexpression of EGFR has, in some studies, been associated with a poor prognosis underlining the significant role EGFR may have in human gastric cancer biology." (PMID 20068568, 2010). "EGFR pathway has also been implicated in pathophysiology of esophageal and stomach cancers." (PMID 19750187, 2009). "On this basis, we considered that searching for EGFR alterations in gastric cancer might have been important to identify therapy susceptible cases." (PMID 18199332, 2008).